SLC16A9 (solute carrier family 16 member 9)
Description:
Extracellular pH-and Na(+)-sensitive low-affinity creatine transporter. Also functions as a pH-independent carnitine efflux transporter.
Synonyms: C10orf36; MCT9; FLJ43803
Tractability: Antibody: UniProt places it where antibodies can reach, with high confidence; its Gene Ontology location is reachable by antibodies, with high confidence; UniProt predicts a signal peptide or a membrane-spanning region. PROTAC: ubiquitination databases record sites on it.
Gene: Protein-coding gene on chromosome 10 (59,650,762 to 59,736,002, reverse strand). Ensembl gene ENSG00000165449.
Subcellular location: Cell membrane
Subcellular location (Human Protein Atlas): Nucleoplasm; Cell Junctions
Gene Ontology:
Molecular function: carnitine transmembrane transporter activity; creatine transmembrane transporter activity; protein binding; monocarboxylic acid transmembrane transporter activity; transmembrane transporter activity
Biological process: carnitine transmembrane transport; creatine transmembrane transport; urate metabolic process; carboxylic acid transmembrane transport; transmembrane transport
Cellular component: plasma membrane
Genetic constraint (gnomAD): Loss-of-function variants: 19 observed, 39.84 expected, observed/expected ratio (o/e) 0.48, 90% interval 0.33 to 0.7. The upper end of that interval is the gene's LOEUF score, 0.7, which puts it in group 2 of 6, group 1 being the genes least tolerant of losing a copy. Missense variants: 523 observed, 578.86 expected, observed/expected ratio (o/e) 0.9, 90% interval 0.84 to 0.97. Synonymous variants: 213 observed, 217.57 expected, observed/expected ratio (o/e) 0.98, 90% interval 0.88 to 1.1.
Homologues: Orthologues: macaque SLC16A9 (98% identical), pig SLC16A9 (93% identical), dog SLC16A9 (92% identical), guinea pig SLC16A9 (91% identical), chimpanzee SLC16A9 (89% identical), mouse Slc16a9 (88% identical), rat Slc16a9 (87% identical), rabbit SLC16A9 (86% identical), tropical clawed frog slc16a9 (60% identical), zebrafish slc16a9a (51% identical), zebrafish slc16a9b (49% identical), Drosophila melanogaster CG13907 (27% identical), and 12 more. Paralogues in human: SLC16A14 (29% identical), SLC16A8 (25% identical), SLC16A12 (24% identical), SLC16A10 (24% identical), SLC16A3 (24% identical), SLC16A13 (23% identical), SLC16A4 (23% identical), SLC16A6 (23% identical), SLC16A11 (22% identical), SLC16A7 (22% identical), SLC16A1 (22% identical), SLC16A2 (22% identical), and 1 more.
Diseases named in the same sentence as SLC16A9 in open-access papers:
SLC16A9 is named in the same sentence as 22 diseases in open-access papers, as found by Europe PMC text mining. Sharing a sentence is not in itself a finding about the gene and the disease. The quoted sentences say what the papers report.
gout (14 papers, 2013 to 2025). A condition characterized by painful swelling of the joints, which is caused by deposition of urate crystals. "The significant associations of SLC16A9 expression in adipose and arterial tissues suggest a potential link to adiposity, a known risk factor for gout." (PMID 41075270, 2025). "The genetic polymorphism rs1171614 (C > T) in SLC16A9 was reported to influence SU levels and the risk of gout." (PMID 33810064, 2021). "At SLC16A9, the observed association with gout was restricted to the lower Polynesian ancestry group (rs12356193, P=0.006)." (PMID 32090094, 2020). "Taken together, WES revealed a putative causal variant in SLC16A9 in a family with early-onset gout." (PMID 32090094, 2020). "A few studies supported our results of the association between SLC16A9 and gout and serum urate levels." (PMID 32090094, 2020). "To elucidate the genetic predisposition, whole-exome sequencing (WES) was performed, and we identified a rare missense mutation (c.277C>A, p.L93M) in SLC16A9, providing new evidence for the association of SLC16A9 with gout." (PMID 32090094, 2020). "In conclusion, we provide the first evidence for the association of rare missense in SLC16A9 with early-onset gout." (PMID 32090094, 2020). "The even weaker evidence for association of SLC16A9 with gout in Köttgen and colleagues (OR = 1.10, P = 0.017) was also not replicated elsewhere (OR = 1.01)." (PMID 25889045, 2015). "Interestingly, our previous study reported an association between SLC16A9 and gout, and SLC16A9 is known to be associated with carnitine levels." (PMID 35372350, 2022). "ALDH16A1 gene is associated with serum uric acid levels and gout, and RNA sequencing in the kidney of wild-type (WT) and Aldh16a1 knockout (KO) mice revealed changes in Slc16a9 are localized to the apical membrane of the proximal convoluted tubule cells and influence uric acid homeostasis." (PMID 32090094, 2020). "A few studies supported our results of the association between SLC16A9 and gout." (PMID 32090094, 2020). "To date, the transport substrate of MCT9 is still unknown and the function of SLC16A9 remains poorly understood, especially its potential association with gout." (PMID 32090094, 2020). "Transcriptome-wide association studies highlighted several genes, such as SLC16A9 and ASAH2B, which showed significant expression patterns across various tissues, implicating metabolic and immune pathways in gout." (PMID 41075270, 2025). "Among the other genes significantly associated with gout, seven loci have also been previously identified in GWAS, including those in the genes SLC17A1, GCKR, SLC22A11, ADH1B, MLXIPL, RREB1 and SLC16A9." (PMID 41075270, 2025). "According to GWAS studies, SLCs including SLC2A9, SLC16A9, SLC17A1, SLC17A3, SLC22A11, and SLC22A12 were risk loci for gout." (PMID 30239845, 2019). "In future clinical and epidemiological studies, it will be important to investigate why loci such as SLC16A9 and SLC22A11 inconsistently associate with gout." (PMID 25889045, 2015). "This suggests that if we can clearly clarify the specific mechanism of SLC16A9 on gout in future research, which may provide an effective target for the precise treatment of gout." (PMID 35922835, 2022). "The genetic screening of SLC16A9 in gout pedigrees is required in the future studies." (PMID 32090094, 2020). "Rs2242206 of SLC16A9 gene was associated with ROL gout but not with overall gout in a Japanese male cohort." (PMID 30123371, 2018). "Previous studies identified several transporter genes associated with gout, such as ATP-binding cassette transporter, subfamily G, member 2 (ABCG2/BCRP), GLUT9/SLC2A9, monocarboxylate transporter 9 (MCT9/SLC16A9), and organic anion transporter 4 (OAT4/SLC22A11)." (PMID 24318514, 2014). "In addition, SLC16A9 SNPs are closely related to the occurrence and development of gout." (PMID 35922835, 2022). "However, a role for variants of SLC16A9 and gout itself has not been demonstrated." (PMID 32090094, 2020).
gout (continued). "Recent reports also show the significance of transporter genes such as ABCG2, NPT1/SLC17A1, MCT9/SLC16A9, and OAT4/SLC22A11, for the pathogenesis of gout." (PMID 24366390, 2014). "Although it has been confirmed that there is a remarkable correlation between SLC16A9 gene and different types of gout, its specific regulatory mechanism is not clear." (PMID 35922835, 2022). "The physiological roles of SLC16A9 in gout are related to intestinal urate clearance rather than decreased renal urate excretion." (PMID 30239845, 2019).
colorectal cancer (3 papers, 2020 to 2023). A primary or metastatic malignant neoplasm that affects the colon or rectum. "Three novel genes, CNTN3, SLC1A1, and SLC16A9 were shown to have diagnostic value with respect to the occurrence of colorectal cancer and should be verified in future studies." (PMID 32566650, 2020).
colon cancer (1 paper, 2021). "In mRNAs, SLC16A9 is found to be associated with OS in colon cancer patients (P = 2.248e−02)." (PMID 33832120, 2021). "More related molecular experiments should be performed to explore the role of SLC16A9 in colon cancer." (PMID 33832120, 2021). "High expression of SLC16A9 leads to improved OS in colon cancer patients." (PMID 33832120, 2021).
hepatitis B (1 paper, 2017). "SLC16A9 is responsible for carnitine efflux transport and mutations in the gene have resulted in differential immune response in hepatitis B patients." (PMID 29030588, 2017).
kidney tumors (1 paper, 2023). "SLC16A9 was highly expressed in the C3 (inflammatory) and C4 (lymphocyte depleted) immune subtypes of all three different subtypes of kidney tumors (KICH, KIRC and KIRP), and it was lowly expressed in the C2c-CIMP molecular subtype of KIRP." (PMID 37047552, 2023).
triple-negative breast carcinoma (1 paper, 2025). An invasive breast carcinoma which is negative for expression of estrogen receptor (ER), progesterone receptor (PR), and human epidermal growth factor receptor 2 (HER2). "For instance, EZH2- and PKM2-mediated co-silencing of SLC16A9 in triple-negative breast cancer (TNBC) induces a metabolic shift from glycolysis to fatty acid oxidation, highlighting potential for synthetic lethality via dual-targeting strategies." (PMID 40842995, 2025).
cancer (5 papers, 2020 to 2025). A tumor composed of atypical neoplastic, often pleomorphic cells that invade other tissues. "For CSS, patients with cancer-specific death presented higher expression patterns of RGPD8, BAIAP2L1, and DDX11 and lower expression patterns of SLC16A9, FRAS1, AQP1, TMEM38B, and PRUNE2, in both the univariate and multivariate analyses." (PMID 31963294, 2020). "MIR205HG, PIWIL1, and SLC16A9 are the only genes that were upregulated in cancer samples across all racial groups, but they do not impact survival." (PMID 40558258, 2025).
intestinal diseases (2 papers, 2020 to 2023). "Currently, there is not any research on the increased expression of SLC16A9 associated with intestinal diseases." (PMID 36854781, 2023). "At present, there is still a lack of research into SLC1A1, SLC16A9, and CNTN3 related to intestinal diseases." (PMID 32566650, 2020).
tumor (2 papers, 2020 to 2024). "Impaired histone methyltransferase, enhancer of zeste homolog 2 (EZH2), can be recruited to solute carrier family 16 member 9 (SLC16A9), a carnitine transporter, coordinated by the direct interaction of PKM2, thus epigenetically influencing tumor progression." (PMID 39484162, 2024).
SLC16A9 also shares sentences with these, for which no sentence is quoted: breast carcinoma (2 papers); colorectal adenoma (2); hyperuricemia (2); ulcerative colitis (2); cardiovascular diseases (1); diffuse large B-cell lymphoma (1); glioblastoma (1); malignant adrenocortical tumors (1); metabolic disorders (1); neurodegenerative disease (1); Obesity (1); type 2 diabetes (1); uterine diseases (1).